FLVCR1 (FLVCR choline and heme transporter 1)
Diseases named in the same sentence as FLVCR1 in open-access papers:
FLVCR1 is named in the same sentence as 49 diseases in open-access papers, as found by Europe PMC text mining. Sharing a sentence is not in itself a finding about the gene and the disease. The quoted sentences say what the papers report.
retinitis pigmentosa (10 papers, 2014 to 2025). Retinitis pigmentosa (RP) is an inherited retinal dystrophy leading to progressive loss of the photoreceptors and retinal pigment epithelium and resulting in blindness usually after several decades. "FLVCR1 mutations have been documented in patients with a rare neurodegenerative disorder, posterior column ataxia with retinitis pigmentosa, whereas FLVCR2 mutations are associated with Fowler syndrome, a rare proliferative vascular disorder of the brain." (PMID 36288320, 2022). "Mutations in FLVCR1 gene have been reported in distinct disorders affecting the sensory nervous system: Posterior Column Ataxia and Retinitis Pigmentosa, Retinitis Pigmentosa and Hereditary Sensory and Autonomic Neuropathy, as reviewed below." (PMID 30356807, 2018). "Flvcr1 gene mutations have been identified as the cause of PCARP (posterior column ataxia with retinitis pigmentosa (PCARP).There are three paralogs of FLVCR1 in the human genome." (PMID 29055035, 2017). "Mutations in the heme exporter FLVCR1 are associated with three distinct disorders affecting the sensory nervous system: posterior column ataxia and retinitis pigmentosa (PCARP), non-syndromic retinitis pigmentosa (RP) and hereditary sensory and autonomic neuropathy (HSAN)." (PMID 30231533, 2018). "In addition, mutations in the FLVCR1 gene have been associated with posterior column ataxia with retinitis pigmentosa (PCARP)." (PMID 27353947, 2016). "However, FLVCR1 is ubiquitously expressed and the observation that mutations in the FLVCR1 gene cause sensory ataxia and retinitis pigmentosa was completely unexpected." (PMID 24782769, 2014). "Missense variants in FLVCR1 cause posterior column ataxia with retinitis pigmentosa, and homozygous protein-truncating variants have never been reported, though removal of Flvcr1 in mice is embryonic lethal." (PMID 38296890, 2024). "Recently, FLVCR1 mutations have been reported in some patients with retinitis pigmentosa (RP) without evidences of posterior column degeneration or cerebellar degeneration." (PMID 30356807, 2018).
synovial sarcoma (6 papers, 2019 to 2024). "Our study was preceded by a series of works reporting increased FLVCR1 expression in bovine papillomavirus-associated urinary bladder cancer, human synovial sarcoma, and human hepatocellular carcinoma." (PMID 38581583, 2024). "The expression of FLVCR1 has been reported up-regulated in different kinds of tumors, including bovine papillomavirus-associated urinary bladder cancer, synovial sarcoma, and hepatocellular carcinoma." (PMID 32010627, 2019). "In synovial sarcoma cells, the silencing of FLVCR1 was associated to reduced cell proliferation, survival and tumorigenicity in vitro and in vivo." (PMID 32010627, 2019). "In synovial sarcoma cells, when FLVCR1 was silenced, it resulted in reduced cell proliferation, diminished cell survival, and decreased tumorigenicity both in vitro and in vivo." (PMID 38581583, 2024). "FLVCR1 regulates the development of synovial sarcoma by inhibiting apoptosis and autophagy, but its role in HCC still needs to be determined." (PMID 35907846, 2022). "For instance, upregulated FLVCR1 promoted the cellular proliferation of neuroblastoma and synovial sarcoma." (PMID 33842377, 2021). "FLVCR1 can promote the proliferation of synovial sarcoma by inhibiting apoptosis and autophagy." (PMID 36894886, 2023).
Diamond-Blackfan anemia (5 papers, 2011 to 2024). A congenital aregenerative and often macrocytic anemia with erythroblastopenia. "The most severely affected individuals, including three individuals with homozygous pLoF variants, share traits with Flvcr1 knockout mice and Diamond-Blackfan anemia including macrocytic anemia and congenital skeletal malformations." (PMID 38405817, 2024). "While Flvcr1 knockout mice die in utero with skeletal malformations and defective erythropoiesis reminiscent of Diamond-Blackfan anemia, rare biallelic pathogenic FLVCR1 variants are linked to childhood or adult-onset neurodegeneration of the retina, spinal cord, and peripheral nervous system." (PMID 38405817, 2024). "However, the mouse knockout of Flvcr1 is known to phenocopy Diamond-Blackfan anemia." (PMID 38098057, 2023).
hepatocellular carcinoma (5 papers, 2019 to 2025). A malignant tumor that arises from hepatocytes. "The overexpression of FLVCR1 in hepatocellular carcinoma is associated with higher disease staging, vascular invasion, histologic grade, and poorer outcomes." (PMID 33842377, 2021). "In a previous study, overexpression of FLVCR1 was known to be strongly associated with poorer survival outcomes of patients with hepatocellular carcinoma." (PMID 33842377, 2021). "For hepatocellular carcinoma, the high expression of FLVCR1 was associated to higher neoplasm disease staging, adjacent tissue inflammation, vascular invasion and neoplasm histologic grade, as well as to reduced overall survival and disease-free status." (PMID 32010627, 2019). "In the case of hepatocellular carcinoma, elevated FLVCR1 expression was linked to more advanced disease staging, inflammation in adjacent tissues, vascular invasion, higher neoplasm histologic grade, and, notably, reduced overall survival and disease-free status." (PMID 38581583, 2024). "Aberrant expression of FLVCR1 was correlated with aggressive tumor stage and poor survival in hepatocellular carcinoma." (PMID 33842377, 2021). "For example, a four-gene signature (ABCB6, FLVCR1, SLC48A1, and SLC7A11) was created to build diagnostic and prognostic models for hepatocellular carcinoma (HCC)." (PMID 40002678, 2025).
anemia (3 papers, 2010 to 2019). A reduction in the number of red blood cells, the amount of hemoglobin, and/or the volume of packed red blood cells. "FLVCR1 has been initially identified as the receptor for Feline Leukemia Virus subgroup C (FeLV C) causing a severe erythroid aplasia in cats similar to the anemia seen in DBA patients, suggesting that FLVCR1 plays a fundamental role during erythropoiesis." (PMID 20454576, 2010). "Also when FLVCR1 expression is deleted postnatally, mice develop severe anemia." (PMID 20454576, 2010).
Posterior Column Ataxia and Retinitis Pigmentosa (3 papers, 2016 to 2024). "Mutations in the human FLVCR1 gene were previously associated to Posterior Column Ataxia and Retinitis Pigmentosa (PCARP)." (PMID 27923065, 2016). "One of the most significant clinical manifestations of FLVCR1 mutations is Posterior Column Ataxia and Retinitis Pigmentosa (PCARP)." (PMID 39765770, 2024). "However, disruptions in heme homeostasis—due to mutations in heme transporters such as FLVCR1 or impaired heme–regulatory protein interactions—can result in neurodegenerative diseases, including Posterior Column Ataxia and Retinitis Pigmentosa (PCARP), Alzheimer’s disease, and Parkinson’s disease." (PMID 39765770, 2024).
aplastic anaemia (2 papers, 2012 to 2020). "FLVCR1 was first discovered for its role in aplastic anaemia in domestic cats and subsequently erythroblast destruction in vitro." (PMID 31963381, 2020).
Fowler syndrome (2 papers, 2022 to 2024). "Considering the clinical overlap, it is likely that homozygous loss of function variants in FLVCR1 also cause a presentation consistent with Fowler Syndrome." (PMID 38296890, 2024).
lung carcinoma (2 papers, 2022 to 2024). "HMBS and FLVCR1 were the most upregulated heme biosynthesis genes in tumor cells from three different NSCLC lung cancer patients." (PMID 39062740, 2024). "Inhibition of FLVCR1 in breast and lung cancer cells resulted in dramatic reductions in proliferation, migration, invasion but acceleration in apoptosis." (PMID 35163973, 2022). "Breast and lung cancer cells exhibit abnormal upregulation of the feline leukemia virus subgroup C receptor 1 (FLVCR1) heme-exporter." (PMID 35163973, 2022). "Similarly, the ratio between the heme/porphyrin exporter FLVCR1 and importer FLVCR2 genes indicates enhanced exporting function in lung cancers." (PMID 39062740, 2024).
Sepsis (2 papers, 2023). Sepsis is defined as life-threatening organ dysfunction caused by a dysregulated host response to infection. "Importantly, we identified six critical genes, including CS, CYP1B1, FLVCR1, IFIT2, MAPK14, and PID1, which showed favorable diagnostic value in screening sepsis samples from normal samples." (PMID 37398680, 2023). "We found that the expression of MAPK14 and CYP1B1 was distinctly increased in sepsis samples compared with normal samples, while the expression of PID1, CS, FLVCR1, and IFIT2 was distinctly decreased in sepsis samples compared with normal samples." (PMID 37398680, 2023). "Using bioinformatics techniques, we identified PID1, CS, CYP1B1, FLVCR1, IFIT2, and MAPK14 as six MRGs that are essential in the course of sepsis." (PMID 37398680, 2023). "Finally, we collected 15 sepsis samples and 15 normal samples and performed RT-PCR to examine the expression of CS, CYP1B1, FLVCR1, IFIT2, MAPK14, and PID1 in our cohort, which further confirmed our previous findings." (PMID 37398680, 2023).
type 2 diabetes (2 papers, 2017 to 2024). "We aimed to investigate AT heme and expression of heme exporter (FLVCR1) in association with obesity and type 2 diabetes (T2D)." (PMID 28706239, 2017). "The main finding of the present study was that adipose tissue heme and FLVCR1 mRNA levels were increased in AT from patients with type 2 diabetes in direct proportion to fasting glucose levels, but not in association with BMI." (PMID 28706239, 2017).
Ataxia (1 paper, 2020). Ataxia refers to impaired coordination of voluntary muscle movement. "We, therefore, supplemented the EOAD- control group with ataxia genotypes that were not reported with comorbid dystonia in literature (including ABHD12; IFRD1; KIAA0226; PHYH; TDP1; VWA3B; GTF2H5; FLVCR1; ACO2; HSD17B4; DNAJC3 gene mutations; PubMed and OMIM)." (PMID 33255407, 2020).
autonomic neuropathies (1 paper, 2021). "The authors mainly referred to recent findings showing that loss-of-function variants of the gene encoding for the heme export protein FLVCR1 (feline leukemia virus subgroup receptor 1) can cause hereditary sensory and autonomic neuropathies with a loss of pain perception." (PMID 34639197, 2021).
disc degeneration (1 paper, 2022). "We identified four genes (SOX9, FLVCR1, NR5A1 and UCHL1) associated with mitochondrial dysfunction that play an important role in the progress of disc degeneration." (PMID 36267810, 2022).
dystroglycanopathy (1 paper, 2024). "In S5, we identified a likely pathogenic variant in FLVCR1, which is not a known cause of dystroglycanopathy." (PMID 38296890, 2024).
esophageal squamous cell carcinoma (1 paper, 2021). Esophageal squamous cell carcinoma (ESCC) is a type of esophageal carcinoma (EC) that can affect any part of the esophagus, but is usually located in the upper or middle third. "However, the expression and role of FLVCR1 in esophageal squamous cell carcinoma (ESCC) remain largely unknown." (PMID 33842377, 2021).
iron deficiency (1 paper, 2014). "Analysis of FLVCR1 expression in a population of pregnant adolescents at high risk of iron deficiency showed that FLVCR1 was downregulated in placentas of anemic mothers at term." (PMID 25071574, 2014).
lymph node metastasis (1 paper, 2021). "Upregulated FLVCR1 was positively correlated with lymph node metastasis (N stage) and late tumor-node-metastasis (TNM) stage." (PMID 33842377, 2021).
neuropathies (1 paper, 2023). "The data expand the spectrum of disease-relevant alterations in CIP/HSAN, including novel variants in previously rarely recognized entities such as ATL3-, FLVCR1- and NGF-associated neuropathies and previously under-recognized mutation types such as larger deletions." (PMID 37769650, 2023).
ovarian carcinoma (1 paper, 2023). A malignant neoplasm originating from the surface ovarian epithelium. "The expression of most genes involved in iron export, including ABCG2, FLVCR1, FLVCR2, and SLC40A1, was associated with improved PFS in ovarian cancer." (PMID 38186569, 2023). "Similarly, for iron export, lower expression levels of ABCG2, FLVCR1, and FLVCR2 were associated with an advanced stage of ovarian cancer." (PMID 38186569, 2023). "Similarly, most genes involved in iron export, such as SLC40A1, FLVCR1, ABCG2, and MON1A, displayed reduced expression in ovarian cancer tissues; in contrast, only one gene, FLVCR2, showed the opposite trend." (PMID 38186569, 2023).
porphyria (1 paper, 2016). Porphyria is a group of diseases in which substances called porphyrins build up, negatively affecting the skin or nervous system. "Although elevated porphyrins are a hallmark of multiple types of porphyria, the role of porphyrin transporters (TSPO, ABCG2, ABCB6 and FLVCR1) as modulators of disease severity has not been investigated." (PMID 27507172, 2016).
red cell aplasia (1 paper, 2012). "The switch in subgroup from A to C in cats with pure red cell aplasia is marked by amino acid alterations in the RBD that shift receptor usage from THTR1 to the haem transporter FLVCR1." (PMID 22650160, 2012).
Sensory neuropathy (1 paper, 2016). Peripheral neuropathy affecting the sensory nerves. "We demonstrated that sensory neuropathy-associated FLVCR1-mutations compromise the ability of FLVCR1a to export heme." (PMID 27923065, 2016). "The finding of FLVCR1 mutations in patients with peripheral sensory neuropathy suggests that heme metabolism via FLVCR1a plays an essential role for maintenance of these specialized neurons." (PMID 27923065, 2016). "Together, these data link FLVCR1 mutations to early-onset complicated sensory neuropathy." (PMID 27923065, 2016).
Walker Warburg Syndrome (1 paper, 2024). "Indeed, a homozygous protein truncating variant in FLVCR1 gene was identified in a patient with a clinical diagnosis of Walker Warburg Syndrome (WWS), a severe form of dystroglycanopathy-type congenital muscular dystrophy." (PMID 38581583, 2024).
tumor (12 papers, 2019 to 2025). "In this study, CSE1L was identified as a novel downstream target of FLVCR1 and implicated in the regulation of tumor growth and migration in ESCC." (PMID 33842377, 2021). "Notably, the increased expression of the heme export gene FLVCR1 was found in tumor progression, and associated with poor survival, indicating a significant role of heme and porphyrin trafficking in shaping the tumor microenvironment." (PMID 39199347, 2024). "In over 80% of all tumors, the genes for hydroxymethylbilane synthase (HMBS), the third enzyme of the heme biosynthetic pathway, and the heme exporter FLVCR1 were among the most commonly up-regulated across diverse tumor types." (PMID 38649187, 2024). "Another study found that ABCB6 and FLVCR1 (an important carrier of cell surface heme output) were strongly positive and synergetic in tumor tissue, and were significantly down regulated after erastin intervention." (PMID 36406272, 2022). "The role of FLVCR1 in tumor growth and metastasis was further investigated in a tumor-bearing mouse model." (PMID 33842377, 2021). "Effectively, in HCC tumors, the increased expression levels of Fe-related FLVCR1 and TFRC genes were associated with various factors leading to poor prognosis such as vascular invasion and the histological grade of the tumor for FLVCR1." (PMID 33255972, 2020). "Similarly, there were significant expression differences for RDM1, CDCA3 and FLVCR1 within different tumor stages." (PMID 41048998, 2025). "Finally, the FLVCR1 gene is overexpressed in most tumors, and this contributes to metabolic adaptation that sustains tumor growth." (PMID 38397386, 2024). "In summary, these results suggest that FLVCR1 may function as an oncoprotein during the process of tumor development." (PMID 33842377, 2021). "Recent studies have focused on the crucial role of FLVCR1 in tumor promotion." (PMID 33842377, 2021). "Therefore, we will focus on the relationship between FLVCR1 and tumor-infiltrating CD8+ T cells or peripheral CD8+ T cells in ESCC in further studies." (PMID 33842377, 2021). "As a result, inhibition of FLVCR1 slowed the tumor growth of KYSE-150 cells in vivo." (PMID 33842377, 2021). "Furthermore, the vital role of FLVCR1 in tumorigenesis and migration of ESCC was confirmed in a tumor-bearing mouse model." (PMID 33842377, 2021). "The results of Co-IP showed the interaction between CSE1L and FLVCR1, indicating that CSE1L might be required for FLVCR1-mediated tumor promotion in ESCC." (PMID 33842377, 2021).
cancer (8 papers, 2021 to 2025). A tumor composed of atypical neoplastic, often pleomorphic cells that invade other tissues. "Beyond the disorders arising from FLVCR1 gene mutation, multiple studies indicate that FLVCR1a dysregulation is linked to additional pathological conditions, as diabetes and cancer and, especially for cancer, FLVCR1a dysregulation appears to be harnessed for disease maintenance and/or initiation." (PMID 38581583, 2024). "Furthermore, specific disorders resulting from mutations in FLVCR1 gene have been documented, and FLVCR1a dysregulation has been associated with various pathological conditions, including cancer." (PMID 38581583, 2024). "While interaction between genes is complex, if a gene is essential to survival of a cancer cell line, we may a priori expect a worse prognosis is likely to be associated with higher expression, as in the case of FLVCR1 and TCF3." (PMID 35882937, 2022). "The cancer progenitor cells also had a higher expression level of genes related to heme trafficking such as FLVCR1 and DNM2." (PMID 38649187, 2024).
infection (3 papers, 2012 to 2021). The state of being infected such as from the introduction of a foreign agent such as serum, vaccine, antigenic substance or organism. "The development of FeLV-C from the initial infection with a FeLV-A isolate is accompanied by an alteration in the receptor usage of the virus, from the thiamine transporter THTR1 utilised by FeLV-A to the haem transporter, FLVCR1 utilised by FeLV-C." (PMID 22650160, 2012).
neurodegenerative disease (1 paper, 2024). A disorder of the central nervous system characterized by gradual and progressive loss of neural tissue and neurologic function. "Mutations in Feline Leukemia Virus Subgroup C Receptor 1 (FLVCR1), a critical heme transporter, lead to impaired heme export, disrupting heme homeostasis and resulting in neurodegenerative diseases." (PMID 39765770, 2024).
FLVCR1 also shares sentences with these, for which no sentence is quoted: hereditary sensory and autonomic neuropathy (3 papers); neuroblastoma (2); sensory ataxia (2); Usher syndrome (2); Alzheimer disease (1); amyotrophic lateral sclerosis (1); aplastic anemia (1); bacterial infection (1); Bardet-Biedl syndrome (1); ciliopathy (1); Dystonia (1); esophageal cancer (1); gastric cancer (1); glaucoma (1); Hydrocephalus (1); Hyperglycemia (1); macrocytic anemia (1); malaria (1); Obesity (1); Parkinson disease (1); pneumococcal infection (1).